KCNAB1 (potassium voltage-gated channel subfamily A regulatory beta subunit 1)
Description:
Regulatory subunit of the voltage-gated potassium (Kv) Shaker channels composed of pore-forming and potassium-conducting alpha subunits and of regulatory beta subunits. The beta-1/KCNAB1 cytoplasmic subunit mediates closure of delayed rectifier potassium channels by physically obstructing the pore via its N-terminal domain and increases the speed of channel closure for other family members. Promotes the inactivation of Kv1.1/KCNA1, Kv1.2/KCNA2, Kv1.4/KCNA4, Kv1.5/KCNA5 and Kv1.6/KCNA6 alpha subunit-containing channels. Displays nicotinamide adenine dinucleotide phosphate (NADPH)-dependent aldoketoreductase activity by catalyzing the NADPH-dependent reduction of a variety of endogenous aldehydes and ketones (By similarity). The binding of NADPH is required for efficient down-regulation of potassium channel activity. Oxidation of the bound NADPH restrains N-terminal domain from blocking the channel, thereby decreasing N-type inactivation of potassium channel activity (By similarity).
Synonyms: KCNA1B; AKR6A3; hKvBeta3; Kvb1.3; hKvb3; KV-BETA-1
Tractability: Antibody: UniProt places it where antibodies can reach, with high confidence; its Gene Ontology location is reachable by antibodies, with high confidence. PROTAC: ubiquitination databases record sites on it; a small molecule that binds it is known.
Target class: Voltage-gated potassium channel beta-subunit family; Auxiliary transport protein
Safety:
Unwanted effects reported when the protein is acted on. In parentheses: how it was acted on, where the effect was seen, and who reports it.
hypertension (source: ClinPGx)
Gene: Protein-coding gene on chromosome 3 (156,037,701 to 156,538,756, forward strand). Ensembl gene ENSG00000169282.
Subcellular location: Cytoplasm; Membrane; Cell membrane
Subcellular location (Human Protein Atlas): Vesicles; Nucleoplasm; Plasma membrane
Pathways (Reactome):
Neuronal System: Voltage gated Potassium channels
Gene Ontology:
Molecular function: molecular function inhibitor activity; NADPH binding; potassium channel regulator activity; protein binding; protein domain specific binding; alcohol dehydrogenase (NADP+) activity; carbonyl reductase (NADPH) activity; transmembrane transporter binding; voltage-gated potassium channel activity
Biological process: potassium ion transmembrane transport; potassium ion transport; regulation of potassium ion transmembrane transport; transmembrane transport
Cellular component: cytoplasm; cytoplasmic side of plasma membrane; cytosol; plasma membrane; potassium channel complex; voltage-gated potassium channel complex; juxtaparanode region of axon; membrane
Genetic constraint (gnomAD): Loss-of-function variants: 14 observed, 28.88 expected, observed/expected ratio (o/e) 0.48, 90% interval 0.32 to 0.76. The upper end of that interval is the gene's LOEUF score, 0.76, which puts it in group 3 of 6, group 1 being the genes least tolerant of losing a copy. Missense variants: 235 observed, 314.85 expected, observed/expected ratio (o/e) 0.75, 90% interval 0.67 to 0.83. Synonymous variants: 119 observed, 127.71 expected, observed/expected ratio (o/e) 0.93, 90% interval 0.8 to 1.09.
Homologues: Orthologues: chimpanzee KCNAB1 (99% identical), macaque KCNAB1 (99% identical), rat Kcnab1 (96% identical), rabbit KCNAB1 (96% identical), pig KCNAB1 (96% identical), guinea pig KCNAB1 (83% identical), mouse Kcnab1 (83% identical), tropical clawed frog kcnab1 (79% identical), dog KCNAB1 (76% identical), zebrafish kcnab1a (75% identical), zebrafish kcnab1b (63% identical), Caenorhabditis elegans Y39G8B.1 (17% identical), and 7 more. Paralogues in human: KCNAB2 (69% identical), KCNAB3 (61% identical), AKR1C8 (20% identical), AKR1B10 (20% identical), AKR1C2 (20% identical), AKR1B1 (19% identical), AKR1C3 (19% identical), AKR1C4 (19% identical), AKR7A2 (19% identical), AKR7A3 (19% identical), AKR1C1 (19% identical), AKR1A1 (19% identical), and 4 more.
Diseases named in the same sentence as KCNAB1 in open-access papers:
KCNAB1 is named in the same sentence as 24 diseases in open-access papers, as found by Europe PMC text mining. Sharing a sentence is not in itself a finding about the gene and the disease. The quoted sentences say what the papers report.
epilepsy (5 papers, 2015 to 2025). A brain disorder characterized by episodes of abnormally increased neuronal discharge resulting in transient episodes of sensory or motor neurological dysfunction, or psychic dysfunction. "This study highlights a potential link between voltage-gated potassium channels and the risk of epilepsy, especially concerning the genetic variations in the KCNAB1 and KCNJ10 genes." (PMID 40142207, 2025). "Within KCNAB1, our finding asserts that both rs3755631 and rs4679773 are correlated to epilepsy; the p-value = 0.04 for both allelic associations." (PMID 40142207, 2025). "Among the possible target candidates, we found the DEG KCNAB1 which belongs to the voltage gate channel group associated with epilepsy." (PMID 38383918, 2024). "In another study, a de novo heterozygous mutation (c.1062dupCA, p.Leu355HisfsTer5) in KCNAB1 was reported as disease causing for epilepsy in a patient with early infantile epileptic encephalopathy." (PMID 29554876, 2018). "Here we reported an epileptic patient with a KCNAB1 mutation, which supports the relationship between KCNAB1 dysfunction and epilepsy, and interestingly, the epileptic discharges of this patient located mostly at temporal region." (PMID 26544041, 2015). "To our knowledge, we are the first to report KCNAB1 is a disease-causing gene of epilepsy by identifying a novel de novo mutation (c.1062dupCA p.Leu355HisfsTer5) within this gene in one patient with early infantile epileptic encephalopathy (EIEE)." (PMID 26544041, 2015). "An association study of 2717 epileptic patients reported that numerous SNPs located within KCNAB1 contributed to the susceptibility to epilepsy." (PMID 26544041, 2015). "In this study, we revealed the association between different genetic variants of voltage-gated potassium channels and epilepsy risk, and, accordingly, we suggest that both rs3755631 and rs4679773 of KCNAB1 are correlated with epilepsy." (PMID 40142207, 2025). "Genetic variants can be used as predictive factors for the recurrence of epilepsy, and in light of our findings, KCNAB1 was found to impact relapse in epilepsy." (PMID 40142207, 2025). "In this study, we implied that KCNJ10 and KCNAB1 may mediate drug responsiveness in epilepsy patients." (PMID 40142207, 2025). "In summary, although several previous studies have supported the association of KCNAB1 with epilepsy, no KCNAB1 mutations have been reported in patients with this disease previously." (PMID 26544041, 2015). "KCNAB1 has been reported as a susceptibility gene for epilepsy, particularly temporal lobe epilepsy (TLE), but no pathogenic mutation has been reported." (PMID 26544041, 2015). "It was found that a family history of epilepsy was influenced by KCNA1/rs2227910, KCNAB1/rs4679773, and KCNJ10/rs12122979 (p-values = 0.039, 0.011, 0.047)." (PMID 40142207, 2025). "The levels of Vitamin D and Vitamin B12 levels among epilepsy patients were influenced by KCNA2 and KCNAB1, respectively." (PMID 40142207, 2025). "Finally, epilepsy classification was correlated with KCNV2/rs10967728 and KCNAB1/rs1551066, KCNJ9/rs2753268 (p-values = 0.033, 0.020, 0.024)." (PMID 40142207, 2025).
Ataxia (2 papers, 2020 to 2022). Ataxia refers to impaired coordination of voluntary muscle movement.
follicular adenomas (2 papers, 2015 to 2020). "Downregulation of KCNAB1 expression has been identified in follicular thyroid carcinomas compared to benign follicular adenomas." (PMID 25922907, 2015).
follicular carcinoma (2 papers, 2013 to 2015). "We confirmed that ELMO1, EMCN, ITIH5, KCNAB1, and SLCO2A1 were downregulated in follicular carcinoma compared to adenoma." (PMID 24099521, 2013).
Hypertension (2 papers, 2014 to 2024). The presence of chronic increased pressure in the systemic arterial system. "The rs6770663 (A>G) variant in KCNAB1 increased the risk of hypertension (p = 4.16 × 10−6)." (PMID 38397167, 2024). "A genome-wide meta-analysis of 1037 patients receiving bevacizumab found that the presence of SNPs in KCNAB1, TRIO and DNAH5 was related to an increased risk of hypertension and proteinuria." (PMID 38397167, 2024).
breast carcinoma (1 paper, 2018). "In cancer genetics, KCNAB1 variation may play a role in breast cancer pathogenesis because its overexpression was found in breast tumors in comparison to non-tumor tissues." (PMID 30545124, 2018).
colon cancer (1 paper, 2024). "QKI has been shown to be an RBP with tumour‐suppressant effects in multiple cancers, including colon cancer, whereas little literature linked KCNAB1 or HIST1H1B with cancer." (PMID 38041531, 2024).
focal epilepsy (1 paper, 2025). A seizure caused by a localized disorder. "Other studies support the fact that KCNAB1 is a vulnerable gene for lateral temporal epilepsy, causing it to alter susceptibility to focal epilepsy." (PMID 40142207, 2025).
Kidney Clear Cell Carcinoma (1 paper, 2022). "In the Cancer Genome Atlas (TCGA) Kidney Clear Cell Carcinoma Illumina HiSeq data, the KCNAB1 level was found to be significantly correlated with the survival rate of renal cancer patients." (PMID 36789694, 2022).
cancer (5 papers, 2018 to 2024). A tumor composed of atypical neoplastic, often pleomorphic cells that invade other tissues. "GWAS studies show that regulatory non-coding variants may play a role in multiple distinct diseases such as cancer and thus the other two intronic variants associated with response (rs2293194 in KCNAB1 and rs4376673 in DFFB) also represent a potential target for further studies." (PMID 30545124, 2018). "These genes are PLAUR, UCN, PABPC1L, SLC16A12, NFE2L3, and KCNAB1, and some of them have been previously reported in multiple types of cancer." (PMID 35211477, 2021). "CELSR3, TRPM2, and TRIP13 are over-expressed in all the 13 cancers, TNXB is under-expressed in all the 13 cancers, KCNAB1 is over-expressed in KIRC but under-expressed in the other 12 cancers." (PMID 30729033, 2019). "However, there is little literature to link KCNAB1 or HIST1H1B with cancer." (PMID 38041531, 2024).
tumor (5 papers, 2010 to 2024). "PLAUR, PABPC1L, SLC16A12, NFE2L3, and KCNAB1 presented significantly different expression levels between tumor tissues and normal tissues." (PMID 35211477, 2021). "In ~70% of the time, hypermethylation of four of these promoters (RASSF1A, CYP26A1, KCNAB1 and SNCA) was detected in adjacent tissues whenever these genes were found to be hypermethylated in the primary tumor by qMSP." (PMID 20226036, 2010).
neurologic disorders (1 paper, 2021). "As for KCNAB1, most studies showed that the potassium channel, voltage-gated subfamily A regulatory beta subunit 1(KCNAB1) is related to neurologic disorders and diseases." (PMID 35211477, 2021).
KCNAB1 also shares sentences with these, for which no sentence is quoted: Epileptic encephalopathy (2 papers); adenoma (1); breast tumors (1); cardiac hypertrophy (1); channelopathies (1); early infantile epileptic encephalopathy (1); edema (1); Episodic Ataxia (1); genetic generalized epilepsy (1); renal carcinoma (1); Spinocerebellar ataxia autosomal recessive 18 (1); temporal lobe epilepsy (1).